FOXL3 (forkhead box L3)
Description:
Probable transcriptional regulator.
Synonyms: WI2-2373I1.2; FOXL3-OT1
Gene: Protein-coding gene on chromosome 7 (290,170 to 294,422, forward strand). Ensembl gene ENSG00000248767.
Subcellular location: Nucleus
Gene Ontology:
Molecular function: DNA-binding transcription factor activity, RNA polymerase II-specific; RNA polymerase II cis-regulatory region sequence-specific DNA binding; DNA-binding transcription factor activity; sequence-specific DNA binding
Biological process: anatomical structure morphogenesis; cell differentiation; regulation of transcription by RNA polymerase II; regulation of DNA-templated transcription
Cellular component: nucleus
Genetic constraint (gnomAD): Loss-of-function variants: 16 observed, 8.68 expected, observed/expected ratio (o/e) 1.84, 90% interval 1.16 to 1.97. That is too few expected variants to judge how well the gene tolerates losing a copy. Missense variants: 400 observed, 240.84 expected, observed/expected ratio (o/e) 1.66, 90% interval 1.53 to 1.8. Synonymous variants: 170 observed, 106.67 expected, observed/expected ratio (o/e) 1.59, 90% interval 1.41 to 1.81.
Homologues: Orthologues: macaque FOXL3 (97% identical), chimpanzee FOXL3 (95% identical), pig FOXL3 (79% identical), dog FOXL3 (77% identical), mouse Foxl3 (71% identical), guinea pig FOXL3 (69% identical), tropical clawed frog foxl3 (57% identical), zebrafish foxl3 (56% identical), rat Foxl3 (53% identical). Paralogues in human: FOXK2 (36% identical), FOXD1 (35% identical), FOXD2 (34% identical), FOXL1 (34% identical), FOXK1 (33% identical), FOXD4L1 (33% identical), FOXC1 (32% identical), FOXD3 (32% identical), FOXC2 (31% identical), FOXD4 (31% identical), FOXD4L3 (30% identical), FOXD4L4 (30% identical), and 29 more.